MIR516B2 (microRNA 516b-2)
Synonyms: hsa-mir-516-3; hsa-mir-516b-2; MIRN516-3; MIRN516B-2; MIRN516B2; mir-516b-2
Gene: MicroRNA gene on chromosome 19 (53,725,442 to 53,725,526, forward strand). Ensembl gene ENSG00000207925.
Gene Ontology:
Biological process: miRNA-mediated post-transcriptional gene silencing